IL6 (interleukin 6)
Diseases named in the same sentence as IL6 in open-access papers (continued):
Sharing a sentence is not in itself a finding about the gene and the disease.
sarcopenia (continued). "IL-6 has been proven as a significant factor in sarcopenia, and the hypothesis from our study adds a new mechanism for IL-6 in the development of sarcopenia." (PMID 39229276, 2024). "Perhaps not surprisingly, IL-6, as an inflammatory marker, has been associated with sarcopenia and cachexia in clinical studies as well as in animal models." (PMID 39683624, 2024). "A meta-analysis published in 2016 indicated that sarcopenia is associated with increased C-reactive protein (CRP) levels but did not confirm the association between sarcopenia and interleukin-6 (IL-6) or tumour necrosis factor α (TNF-α) concentrations." (PMID 38398421, 2024). "The high level of IL‐6 in patients is related to the increase of Lachnoclostridium abundance and the decrease of Streptobacillus abundance, indicating that the abnormal intestinal flora is related to the inflammatory response in sarcopenia patients." (PMID 38270306, 2024). "The only peripheral biomarker associated with mortality was IL-6; however, this was independent of patient sarcopenia status." (PMID 39769198, 2024). "It is postulated that HF, frailty, and sarcopenia share numerous pathophysiological traits, including metabolic dysregulation, systemic inflammation, mitochondrial dysfunction, oxidative stress, and elevated levels of interleukin-6." (PMID 38762515, 2024). "The relationship between IL6 (interleukin‐6) and sarcopenia in individuals aged more than 65 (P = 0.0001) and the relationship between TNFa (tumour necrosis factor alpha) and sarcopenia in all individuals (P = 0.020) have been reported in a meta‐analysis including 80 studies." (PMID 38556722, 2024). "This potential mechanism could explain IL-6 reduction following Ophiocephalus striatus extract supplementation in older adults with sarcopenia." (PMID 38525752, 2024). "First, sarcopenia and PD may share common neuroinflammatory pathways, with elevated interleukin-6 levels observed in patients with both conditions." (PMID 39184585, 2024). "Additionally, circulating levels of IL-6 and IL-10, two sarcopenia-related cytokines, were measured by ELISA." (PMID 38338718, 2024). "In dialysis patients, myostatin (AUC 0.79) and IL-6 (AUC 0.67) had a high discrimination value for sarcopenia, and we were able to develop a prediction model for sarcopenia, including age, albumin, adiponectin, and myostatin levels, with an AUC of 0.806 (95% CI: 0.721–0.891)." (PMID 39125361, 2024). "A growing body of evidence indicates that sarcopenia may impact metabolic abnormalities involving detrimental myokines and hormonal substances, such as Vitamin D, Irisin, IL-6, RANKL, and TNF-α." (PMID 37999432, 2023). "There are contradictory data regarding these last two cytokines, since other studies indicate that patients with sarcopenic obesity (simultaneous presence of sarcopenia and excess adiposity) show high levels of IL-6 and additional inflammatory loads with the presence of adipokines." (PMID 36831134, 2023). "Chronic inflammation also affects sarcopenia, as pro-inflammatory cytokines such as interleukin-6 (IL-6), TNF-α, and C-reactive protein (CRP) increase adiposity and impair the protein synthesis pathway in skeletal muscles, which promotes the pathogenesis of sarcopenia." (PMID 36474318, 2023). "We investigated whether IL-6 is correlated with HCC stage and could represent a diagnostic marker for sarcopenia." (PMID 37173873, 2023). "Moreover, the multivariate binomial logistic regression between sarcopenia and all the variables in the model (BMI, log (IL-6), PMNs/lymphocytes, HCC stages and CP score) showed an AUC of 0.86, a sensibility of 0.91 and a specificity of 0.64." (PMID 37173873, 2023). "Cytokines such as transforming growth factor-β and interleukin-6 may play a role in the development of sarcopenia and contribute to T-cell exhaustion, which can lead to a poor response to immunotherapy." (PMID 37173893, 2023).
sarcopenia (continued). "The aim of our study was to investigate whether high IL-6 levels are correlated with HCC stage and whether it could represent a diagnostic marker for sarcopenia in patients with HCC and cirrhosis." (PMID 37173873, 2023). "Interleukin 6 (IL-6) and tumor necrosis factor alpha (TNF-α) levels may be important factors associated with frailty and sarcopenia, according to a study." (PMID 36776966, 2023). "Interestingly, our subgroup analysis revealed significant benefits of whey protein supplementation on sarcopenia and pre-frailty, highlighting a significant decline in circulating IL-6 levels." (PMID 35706399, 2023). "Patients with peripheral arterial disease (PAD) are more likely to develop sarcopenia through an altered inflammatory process, probably mediated by the deregulation of multiple cytokine-related factors, such as the elevation of IL-6, an IL-1 receptor antagonist, fibrinogen, and CRP." (PMID 36672642, 2023). "Additionally, significantly increased IL-6 (49.77 in sarcopenia vs. 39.72 pg/mL in control) levels have been reported in another cross-sectional study of 441 patients over >60 years of age." (PMID 37299588, 2023). "Shared features of PD with sarcopenia include neuroinflammation mediated by interleukin 6 (IL6)." (PMID 37594550, 2023). "Sarcopenia is also associated with elevated levels of TNF-α, IL-6, and C-reactive protein, suggesting that appropriate treatment for RA may also reduce the development of sarcopenia." (PMID 37239687, 2023). "Most human studies have concentrated on the pro-inflammatory cytokines IL-6 and TNFα contribute to the damaging catabolic effects of inflammation on aging muscle fibers, which leads to skeletal muscle degradation, sarcopenia acceleration, and eventually, a decline in physical performance." (PMID 37465171, 2023). "Em pacientes com IC, a sarcopenia foi associada aos níveis de IL-6 e à capacidade funcional." (PMID 37556651, 2023). "However, whey protein has been shown to lower over-expression of IL-6 in individuals with sarcopenia or frailty." (PMID 37764864, 2023). "The multivariate binomial regression analysis revealed that only log (IL-6) (p = 0.05, Estimate 3.69) demonstrates a nearly significant association with sarcopenia, but not the other variables used in the model (CP score, PMNs/lymphocytes ratio, BMI)." (PMID 37173873, 2023). "Meanwhile, the IL-6 and TNF-α can impair muscle performance, causing sarcopenia." (PMID 37715186, 2023). "Our aim was to investigate whether IL-6 is correlated with HCC stage and could represent a diagnostic marker for sarcopenia." (PMID 37173873, 2023). "Deletion and inhibition of OPA1 also causes mitochondrial dysfunction, increased levels of IL6, IL1, ROS, mitochondrial DNA damage, and subsequent stimulation of transcription factors such as FoxO3 and NF-κB which are associated with sarcopenia and premature death." (PMID 36561214, 2022). "In agreement with our results, a meta-analysis found that levels of CRP but not Interleukin 6 or tumor necrosis factor α were associated with sarcopenia." (PMID 35719155, 2022). "One of the diverse mechanisms known to contribute to the onset of sarcopenia is the slight but persistent increase in inflammatory mediators such as IL-1β, IL-6, and TNF-α that simultaneously impact muscle metabolism, causing wasting and loss via the mTOR pathway." (PMID 35954203, 2022). "Conversely, abdominal obesity might induce sarcopenia via the activation of proinflammatory cytokines, such as interleukin-6 and tumor necrosis factor-a." (PMID 36120449, 2022). "In consideration of this role of IL-6, we hypothesized that IL-17 level may be elevated in patients with sarcopenia, and our results confirmed this hypothesis." (PMID 35237317, 2022).
sarcopenia (continued). "IL-10 and IL-6 concentrations have been seen to be increased in patients with sarcopenia, as well as the IL-6/IL-10 ratio, suggesting that the increase in IL-10 might be a compensatory mechanism elicited to suppress the effects of increased IL-6 expression." (PMID 36499366, 2022). "In addition, IL-6 attenuates muscle anabolism, energy homeostasis, and even directly mediates muscle catabolism, promotes muscle atrophy, and leads to sarcopenia disease." (PMID 36311511, 2022). "Interestingly, CoQ10 protects endothelial cells against inflammatory response and the secretory phenotype preventing the release of IL-6, a known cytokine that affects muscle sarcopenia." (PMID 35204162, 2022). "Logistic regression analysis was carried out to associate the inflammatory markers IL-6, TNF-α, and CRP with sarcopenia, and it was found that TNF-α was the only significant predictor of sarcopenia in tertile 3 or at levels > 71.2 [(OR = 5.85), 95% (1.07–32.08)]." (PMID 36291982, 2022). "Our study has demonstrated that IL-6 and IL-17A were elevated in patients with sarcopenia." (PMID 35237317, 2022). "Physical inactivity, oxidative stress, inflammatory cytokines (such as IL-6 and TNF-α), reduced microvascular flow to muscles, and inadequate energy intake were regarded as common features linked with chronic lung diseases and sarcopenia." (PMID 36388101, 2022). "Overall, mean age, MELD score, lymphocyte count, NLR, TBIL, INR, CRP, IL-6, proportion of sarcopenia, and more than one complication were higher in the patients who experienced progression; conversely, the mean L3 SMI, platelet count, ALT, sodium, and AFP were lower (p < 0.05)." (PMID 35771410, 2022). "The effect of exercise on sarcopenia could be due to its role in altering α-motoneuron properties and impacting muscle fibers through IL-6 and growth hormone." (PMID 35159052, 2022). "Interestingly, some authors reported the presence of a similar cytokine (Interleukin-6 [IL-6]) in both patients with sarcopenia and schizophrenia." (PMID 36090356, 2022). "In addition to activating immune system function against pathogens, IL-6 signaling is also a part of age-related chronic inflammation and is related to the pathogenesis of sarcopenia." (PMID 34112103, 2021). "Finally, sarcopenia is associated with inflammation demonstrated by increased serum C-reactive protein (CRP) levels, interleukin-6 (IL-6), and TNFα." (PMID 35010928, 2021). "Similar to IL-6, TNFα appears crucial in cancer-related sarcopenia." (PMID 33804536, 2021). "The relationships between IL-6 and sarcopenia differs in different studies." (PMID 34911470, 2021). "Among the many features of sarcopenia, increases in pro-inflammatory cytokines, such as IL-6 and TNF-α, may be responsible for the poor prognosis of patients with sarcopenia and endometrial cancer." (PMID 34928453, 2021). "The correlation between interleukin-6 and sarcopenia remains to be further explored." (PMID 34911470, 2021). "There are many common risk factors between sarcopenia and osteoporosis in COPD, including systemic inflammation (such as enhanced tumor necrosis factor (TNF)-α and IL-6), cigarette smoking, hypoxemia and/or hypercapnia, malnutrition, oxidative stress and reduced level of physical activity." (PMID 34650518, 2021). "Thus, owing to its both inflammatory and anti-inflammatory effects, the role of IL-6 is still controversial in sarcopenia." (PMID 33997015, 2021). "Third, sarcopenia is similar to a subclinical state of inflammation, wherein increased levels of circulating pro-inflammatory cytokines, such as IL-6 and TNFα, might potentiate pain sensitivity of the musculoskeletal system." (PMID 34026779, 2021). "In addition, it was found that the level of IL-6 in patients with sarcopenia is independently related to the occurrence of sarcopenia." (PMID 34957238, 2021).
sarcopenia (continued). "Because of the shared pathogenesis of sarcopenia and vitiligo in increased serum IL6, serum cortisol level, low testosterone level, and low vitamin D3 level, so a possible link between sarcopenia and osteoporosis may be present." (PMID 34447910, 2021). "Thus, OLE treatment significantly reduces the IL-6/IL-10 ratio in aged rats, which has been used as a biomarker of sarcopenia in humans." (PMID 34067004, 2021). "To explore the correlation of inflammatory cytokines and sarcopenia, we further utilized Pearson’s correlation to analyse the associations between homocysteine, inflammatory factors (hs-CRP, IL-6) and components of sarcopenia (SMI, grip strength and walking speed)." (PMID 34911470, 2021). "Notably, some studies have suggested how adipocytes, through the release of IL-6 and TNF-α, can promote the accumulation of fat mass and compromise muscle function, thus causing sarcopenia." (PMID 34093446, 2021). "The symptoms of inflammation, i.e. sarcopenia and cachexia, that accompany many cancers may be related to higher IL-6 levels in serum, and they are presently being investigated relative to treatment efficacy also in mCRC." (PMID 32756596, 2020). "Therefore, our findings suggest that 1,25(OH)2D3 can prevent or improve sarcopenia by inhibiting IL-6 production." (PMID 32899782, 2020). "Moreover, a 10-year clinical tracking survey also suggested that the serum concentrations of IL-1β, IL-6 and TNF-α are closely associated with morbidity and mortality in older sarcopenia patients." (PMID 32226296, 2020). "Finally, the beneficial effects of leucine supplementation in this trial seem unrelated to changes in inflammatory markers in blood such as leucocyte counts, reactive C- protein, IL-6 and TNF-alpha, which have all been associated with sarcopenia." (PMID 32230954, 2020). "Importantly, NF-κB-regulated proinflammatory cytokines such as tumour necrosis factor alpha (TNF-α) and interleukin-6 (IL-6) are the most important inducers of muscle waste, particularly in chronic conditions like sarcopenia." (PMID 32751276, 2020). "Based on previous studies arguing for a correlation between systemic inflammation and sarcopenia, we next analyzed circulating levels of IL-10 and IL-6 as surrogates for anti- and pro-inflammatory cytokines in our cohort of patients using multiplex immunoassay." (PMID 31597337, 2019). "Although IL6 can activate the anti-inflammation and muscle proliferation responses after acute exercise, it is usually considered as a pro-inflammatory cytokine involved in the development of age-related inflammation and sarcopenia." (PMID 30696799, 2019). "IL-6 is presumed to play a dual role in the development and progression of sarcopenia." (PMID 30784011, 2019). "Moreover, the central role of IL-6 in the present observations is further emphasized by its role as a biomarker, even an inducer of sarcopenia." (PMID 31423147, 2019). "Finally, we performed multivariate analyses to assess the relationship between sarcopenia and IL-6 levels, IL-10 levels and IL-6/IL-10 ratios." (PMID 30541467, 2018). "We observed positive associations between sarcopenia and levels of IL-6, IL-10 and IL-6/IL-10 ratios, and a negative association between sarcopenia and BMI." (PMID 30541467, 2018). "Higher levels of IL-6 and IL-10 were observed in participants with sarcopenia (P < 0.05)." (PMID 30541467, 2018). "Moreover, it was reported that subjects with abdominal obesity and sarcopenia had high plasma levels of IL-6." (PMID 30077183, 2018). "Interleukin 6, secreted protein acidic and rich in cysteine, macrophage migration inhibitory factor, and insulin-like growth factor 1 levels differed significantly between the normal and sarcopenia groups." (PMID 29872072, 2018). "Another question arises whether pooling male and female data is an accurate way to determine the predictive value of IL-6 in sarcopenia." (PMID 29739343, 2018).
sarcopenia (continued). "Similarly, an inverse correlation has been observed between muscular resistance of hamstrings and serum IL-6 levels in elderly women with OA, suggesting a role for this cytokine in OA sarcopenia." (PMID 29740336, 2018). "Data from the literature show that some inflammatory markers such as IL6, CRP and tumor necrosis factor (TNF) alpha were associated with sarcopenia, and in patients with CKD, these markers were higher than in the patients with normal renal function and were associated with unfavorable outcomes." (PMID 28448584, 2017). "Therefore, exercise can reduce the level of serum IL-6 and inflammatory reaction to reduce the incidence of sarcopenia." (PMID 28701179, 2017). "Therefore, it is likely that the serum IL6 is a more robust predictor of physical condition in apparently healthy yet sarcopenia-prone geriatric populations, due to evidence that IL6 (but not TNFα) tends to be actively produced by the exercising muscle." (PMID 26524964, 2015). "It is noteworthy that IL-6, TNF-α, CRP, and SAA have all been implicated in the pathogenesis of muscle atrophy in the context of sarcopenia or other muscle-wasting disorders." (PMID 25221511, 2014). "Moreover, in aging muscles, the development of sarcopenia is related to increased levels of the proinflammatory cytokines, i.e. tumor necrosis factor α and interleukin 6, and the development of mitochondrial dysfunction." (PMID 25695027, 2014). "Additionally, in cross-sectional studies of the elderly, a decrease in muscle (sarcopenia) correlates with high circulating IL-6." (PMID 22716658, 2012). "There is a growing body of evidence suggesting that sarcopenia is a smoldering inflammatory state driven by cytokines and oxidative stress since elevated levels of interleukin-6 and C-reactive protein are often detected (see “Inflammation and AGING” in Data S1)." (PMID 22096509, 2011). "Indeed, older people with sarcopenia have higher IL-6 levels than those without, and IL-6 levels are associated with sarcopenia." (PMID 40171198, 2025). "In this context, recent investigations have confirmed the high levels of certain proinflammatory markers and cytokines (i.e., tumor necrosis factor alpha (TNF-α), interleukin-6 (IL-6), etc.)in people with sarcopenia, suggesting that VAT mass may act directly or indirectly in SO physiopathology." (PMID 38892578, 2024). "For example, interleukin-6 (IL-6) can be produced by most of the cell type and various tissues under right circumstances, and many researches have studied IL-6 as a pro-inflammatory cytokine with major relationship with lower muscle mass, muscle weakness, and sarcopenia." (PMID 38375321, 2024). "The authors demonstrated that IL-6 was significantly associated with sarcopenia than those without, confirming that inflammaging may represent a valuable link between CKD and sarcopenia." (PMID 39055699, 2024). "However, our MR analysis did not identify a causal relationship between IL-6 or IL-8 and sarcopenia-related traits." (PMID 39193020, 2024). "No causal relationship between IL-6 and sarcopenia traits was observed." (PMID 38750566, 2024). "Lastly, in a cohort consisting of 164 participants aged between 61 and 90 years, it was observed that individuals with sarcopenia exhibited a higher risk of malnutrition and higher levels of IL-6 compared to those without sarcopenia in the initial univariate analysis." (PMID 38032288, 2023). "In addition, IL10TM/TM mice, characterized by a high level of serum IL6, muscle weakness, and high mortality, were employed as a model of sarcopenia because ATP kinetics, high-energy phosphate levels, and energy release from ATP hydrolysis were reduced and inorganic phosphate was increased." (PMID 38069274, 2023). "In addition, IL-6 could be considered a marker of cirrhotic HCC-related sarcopenia, suggesting further investigation with BIA- or CT-dedicated software." (PMID 37173873, 2023).